ACTN2 (actinin alpha 2)
Description:
F-actin cross-linking protein which is thought to anchor actin to a variety of intracellular structures. This is a bundling protein.
Synonyms: CMD1AA; CMH23; CMYO8; CMYP8; MPD6; MYOCOZ
Tractability: Small molecule: a structure with a bound ligand is known; it has a binding pocket of medium quality. Antibody: its Gene Ontology location is reachable by antibodies, with high confidence. PROTAC: UniProt records ubiquitination sites on it; ubiquitination databases record sites on it; its protein half-life has been measured.
Gene: Protein-coding gene on chromosome 1 (236,664,141 to 236,764,631, forward strand). Ensembl gene ENSG00000077522.
Subcellular location: Cytoplasm, myofibril, sarcomere, Z line
Subcellular location (Human Protein Atlas): Actin filaments; Focal adhesion sites; Cytosol; Primary cilium; Primary cilium transition zone
Pathways (Reactome):
Neuronal System: Assembly and cell surface presentation of NMDA receptors; Long-term potentiation; Negative regulation of NMDA receptor-mediated neuronal transmission; Ras activation upon Ca2+ influx through NMDA receptor; Unblocking of NMDA receptors, glutamate binding and activation
Cell-Cell communication: Nephrin family interactions
Hemostasis: Platelet degranulation
Muscle contraction: Striated Muscle Contraction
Signal Transduction: RAF/MAP kinase cascade
Gene Ontology:
Molecular function: channel activator activity; cytoskeletal protein binding; FATZ binding; identical protein binding; phosphatidylinositol-4,5-bisphosphate binding; protein binding; protein domain specific binding; titin binding; titin Z domain binding; transmembrane transporter binding; actin filament binding; integrin binding; structural constituent of muscle; calcium ion binding; LIM domain binding; structural constituent of postsynaptic actin cytoskeleton; structural molecule activity; transcription coactivator activity
Biological process: actin filament uncapping; focal adhesion assembly; microspike assembly; negative regulation of potassium ion transport; negative regulation of protein localization to cell surface; phospholipase C-activating angiotensin-activated signaling pathway; positive regulation of endocytic recycling; positive regulation of potassium ion transport; protein localization to plasma membrane; regulation of membrane potential; sarcomere organization; actin cytoskeleton organization; cell adhesion; muscle cell development; regulation of apoptotic process; anatomical structure formation involved in morphogenesis; cardiac muscle cell development; positive regulation of DNA-templated transcription; postsynaptic actin cytoskeleton organization; supramolecular fiber organization
Cellular component: extracellular exosome; filopodium; focal adhesion; plasma membrane; Z disc; actin filament; cell junction; cortical actin cytoskeleton; cytoskeleton; cytosol; dendritic spine; extracellular region; platelet alpha granule lumen; pseudopodium; actin cytoskeleton; glutamatergic synapse; postsynaptic actin cytoskeleton; postsynaptic density membrane; postsynaptic density, intracellular component; sarcomere; synapse
Genetic constraint (gnomAD): Loss-of-function variants: 36 observed, 110.05 expected, observed/expected ratio (o/e) 0.33, 90% interval 0.25 to 0.43. The upper end of that interval is the gene's LOEUF score, 0.43, which puts it in group 1 of 6, group 1 being the genes least tolerant of losing a copy. Missense variants: 984 observed, 1,199.7 expected, observed/expected ratio (o/e) 0.82, 90% interval 0.78 to 0.87. Synonymous variants: 423 observed, 454.76 expected, observed/expected ratio (o/e) 0.93, 90% interval 0.86 to 1.01.
Gene-disease validity (ClinGen):
ClinGen rates the evidence that ACTN2 causes each of these diseases.
ACTN2-related cardiac and skeletal myopathy (autosomal dominant): Definitive. A cardiac and skeletal muscle disorder caused by variation in the gene ACTN2.
Homologues: Orthologues: guinea pig ACTN2 (99% identical), mouse Actn2 (99% identical), rat Actn2 (99% identical), chimpanzee ACTN2 (99% identical), macaque ACTN2 (99% identical), dog ACTN2 (99% identical), rabbit ACTN2 (99% identical), pig ACTN2 (89% identical), tropical clawed frog actn2 (87% identical), zebrafish actn2b (85% identical), Caenorhabditis elegans atn-1 (62% identical). Paralogues in human: ACTN3 (80% identical), ACTN1 (79% identical), ACTN4 (77% identical), SPTBN1 (30% identical), SPTBN2 (30% identical), SPTBN4 (30% identical), SPTB (29% identical), PLEC (26% identical), SPTBN5 (26% identical), MACF1 (25% identical), DST (25% identical), SYNE1 (24% identical), and 24 more.
Diseases named in the same sentence as ACTN2 in open-access papers:
ACTN2 is named in the same sentence as 79 diseases in open-access papers, as found by Europe PMC text mining. Sharing a sentence is not in itself a finding about the gene and the disease. The quoted sentences say what the papers report.
cardiomyopathy (29 papers, 2014 to 2026). A disease of the heart muscle or myocardium proper. "The ACTN2 variant showed co-segregation with cardiomyopathy, consistent with autosomal dominant inheritance, across 11 affected and 7 healthy family members, and was hence considered pathogenic." (PMID 36899856, 2023). "The possible role of modifier genetic and nongenetic factors adds a further level of complexity in the interpretation of the pathogenicity of ACTN2 variants associated with cardiomyopathy." (PMID 36116040, 2022). "According to the the ClinGen expert panel for HCM, only moderate evidence supports the gene‐disease association between ACTN2 and cardiomyopathies." (PMID 36116040, 2022). "Associations of ACTN2 variants with other types of cardiomyopathies are less strong: ACTN2 p.Gln9Arg variant was identified in the DCM patient." (PMID 33802723, 2021). "Variants in the ACTN2 gene that have been previously reported in individuals with myopathy or cardiomyopathy." (PMID 33802723, 2021). "ACTN2 mutations have been linked to a range of cardiomyopathies, and ACTN4 mutations cause a kidney condition called focal segmental glomerulosclerosis." (PMID 26312134, 2015). "ACTN2 has a long-standing association with cardiomyopathy, however, the first patients with ACTN2-related distal myopathies were first identified in 2019 by Savarese and colleagues, making the gene one of the more recent additions to the growing list of distal-myopathy-associated genes." (PMID 39017652, 2024). "Previous studies have reported that an ACTN2 mutation may lead to diverse cardiomyopathies, including cardiomyopathy, arrhythmia, and LVNC." (PMID 38316882, 2024). "Our data indicate proteopathy as an additional cellular feature caused by the missense ACTN2 variant, which may contribute to human ACTN2-associated cardiomyopathy." (PMID 36078153, 2022). "Genetic variants in α-actinin-2 (ACTN2) are associated with several forms of (cardio)myopathy." (PMID 36078153, 2022). "Based on the severity of cardiomyopathy phenotypes found in this study combined with the recent evidence that ACTN2 is linked to HF, it can be assumed that a patient harboring the homozygous ACTN2 missense variant would develop DCM or RCM leading to HF." (PMID 36078153, 2022). "More specifically, variants in ACTN2 and subsequent alterations in alpha‐actinin‐2 structure or expression have been previously associated with several types of cardiomyopathies (hypertrophic, dilated, and arrhythmogenic), with or without left ventricular compaction." (PMID 36116040, 2022). "The gene ACTN2 was previously known as a causative gene of cardiomyopathies." (PMID 34170073, 2021). "Patients with ACTN2 mutations could present with a wide clinical spectrum including cardiomyopathies and/or other cardiac abnormalities, MsCD, and actininopathy." (PMID 34170073, 2021). "Given the relevance of cross-linkers in determining the physical properties of a cell, we hereby review the cases of inherited cardiomyopathies caused—or likely caused—by aberrant actin-binding and crosslinking proteins, namely alpha-actinin 2 (ACTN2), filamin C (FLNC) and dystrophin." (PMID 32824180, 2020). "However, ACTN2 may be included on comprehensive cardiomyopathy gene panel that includes minor disease-associated genes." (PMID 25224718, 2014). "These include known Mendelian cardiomyopathy risk genes such as FLNC and ACTN2, and novel regulatory candidates like CAMK2D, LMF1, MYOZ1, SKI, SYNPO2L, and TKT." (PMID 41646816, 2026). "While its structural role is well-established, emerging evidence increasingly implicates ACTN2 dysfunction in a spectrum of disorders, including cardiomyopathies, distal myopathies, and neurodegenerative conditions." (PMID 42111349, 2026). "Re-curation of ACTN2 resulted in an increase from moderate to definitive classification for intrinsic cardiomyopathy." (PMID 39132495, 2024).
cardiomyopathy (continued). "Overall, lead variants at 9 of the 61 GWS loci were located nearest to known cardiomyopathy genes (ACTN2, ALPK3, BAG3, FLNC, PLN, TTN), representing significant enrichment (hypergeometric p = 6.01 × 10−11)." (PMID 36376295, 2022). "Through our work, we have showed that, despite sharing the common role of actin-binding and crosslinking proteins, ACTN2, FLNC and DMD mutations can cause different types of cardiomyopathies, ranging from HCM to RCM." (PMID 32824180, 2020). "In conclusion, the Actn2 p.Met228Thr variant does not produce an overt cardiomyopathy phenotype in mice, however, mature male mice display molecular features consistent with HCM." (PMID 36899856, 2023). "Diseases associated with ACTN2 include cardiomyopathy with or without left ventricular noncompaction and myopathy." (PMID 37019990, 2023). "The molecular mechanisms by which missense ACTN2 variants lead to different forms of (cardio)myopathy are not fully understood." (PMID 36078153, 2022). "Previously, ACTN2 mutations have been solely associated with cardiomyopathy, without skeletal muscle disease." (PMID 36116040, 2022). "Pathogenic variants in ACTN2 are rare and do not significantly contribute to cardiomyopathies in numbers." (PMID 33802723, 2021). "ACTN2 is unlikely to be included on an arrhythmogenic gene diagnostic panel or a common cardiomyopathy gene panel in which each gene is responsible for >5% of disease." (PMID 25224718, 2014). "Other highly prioritized genes across multiple lines of evidence include Mendelian cardiomyopathy genes (BAG3, ACTN2, ALPK3)." (PMID 36376295, 2022). "The set of genes identified by the eQTL and sQTL TWAS was enriched for Mendelian cardiomyopathy genes (BAG3, ACTN2) (hypergeometric p = 0.049)." (PMID 36376295, 2022). "Actinin alpha 2 (ACTN2) was also upregulated upon treatment with GSGa, while it has been reported to be downregulated in cardiomyopathy/dilated cardiomyopathy." (PMID 32121252, 2020). "Genes associated with ER stress (e.g., ATF4, NUPR1, DDIT3, TRIB3, CHAC1, SESN2, HERPUD1) were upregulated and genes related to cardiomyopathy and sarcomeric structure (e.g., MYH7, SYNPO2L, LDB3, ACTN2, MYLK3) were downregulated by afatinib, sorafenib, or high-dose ponatinib." (PMID 37069550, 2023). "Hereby, we have reported what has already been discovered about ACTN2, FLNC and dystrophin in inherited cardiomyopathies and our effort might set the stage for broadening the panel of screened genes in cardiomyopathy patients by including the genes that code for other cytoskeletal cross-linkers." (PMID 32824180, 2020). "Besides, cardiomyopathies were not remarkable in all reported patients with ACTN2‐related myopathy, but heart failure or cardiac arrhythmia could be occurred in some patients." (PMID 34170073, 2021). "Two genes (ACTN2 and PLN) best fit an intrinsic (primary) cardiomyopathy phenotype given there were no extracardiac features reported." (PMID 30681346, 2019).
dilated cardiomyopathy (10 papers, 2015 to 2025). Cardiomyopathy which is characterized by dilation and contractile dysfunction of the left and right ventricles. "Variants of uncertain significance (VUS) were found in 17 cases (eight resuscitated and nine dead) in genes associated with HCM or dilated cardiomyopathy (DCM), such as TTN, TNNT2, MYH6, DSP, ACTN2, CALR3, and MYH7." (PMID 36588553, 2022). "We quantified the expression of ACTN2, ZASP and TTN proteins in two patients with dilated cardiomyopathy and compared them with a sex- and age-matched healthy donor." (PMID 36865889, 2023). "Variants in ACTN2 have been reported in patients with HCM, dilated cardiomyopathy, LV noncompaction and restrictive cardiomyopathy." (PMID 39132495, 2024). "The ACTN2 gene (major Z-disc cross-linking protein) is of particular interest as variants within this gene have been linked to diverse cardiac phenotypes such as HCM, dilated cardiomyopathy (DCM), LV non-compaction (LVNC), and SCD." (PMID 39554508, 2024).
heart failure (10 papers, 2020 to 2025). Inability of the heart to pump blood at an adequate rate to meet tissue metabolic requirements. "There was a significant association between nSubLU and ACTN2, previously associated with heart failure, smoking initiation, externalizing behavior, and educational attainment." (PMID 40736093, 2025). "Left ventricular free wall samples were obtained at the time of cardiac transplantation from a heart failure patient with the ACTN2 A868T heterozygous variant." (PMID 37834023, 2023). "The actinin alpha 2 (ACTN2) is one of four encoding isoforms of α-actinin, and genome-wide association and multi-omic analyses reveal ACTN2 as a gene being linked to heart failure." (PMID 34090334, 2021). "ACTN2 is linked with heart failure, especially its mutation that can cause hypertrophic cardiomyopathy." (PMID 32851066, 2020). "Variants of ACTN2 are associated with the development of restrictive cardiomyopathy (RCM), hypertrophic cardiomyopathy (HCM), and heart failure (HF)." (PMID 37834023, 2023). "Nevertheless, these findings are in line with the diminished contractile function in ACTN2mut EHTs, as the patient affected by the homozygous truncating ACTN2 variant (p.Gln860Stop) developed RCM and heart failure (HF) at the age of 23." (PMID 36078153, 2022). "We identify and replicate associations between heart failure and one known locus in chromosome 4 near the PITX2 gene and two novel loci near the ABO (chromosome 9) and ACTN2 (chromosome 1) genes." (PMID 32111823, 2020).
hypertrophic cardiomyopathy (7 papers, 2016 to 2025). A condition in which the myocardium is hypertrophied without an obvious cause. "Missense variants of Z-disk protein, alpha-actinin-2 (ACTN2), have been linked to hypertrophic cardiomyopathy (HCM)." (PMID 40503000, 2025). "Pathogenic variants in ACTN2, coding for alpha-actinin 2, are known to be rare causes of Hypertrophic Cardiomyopathy." (PMID 36899856, 2023). "The heterozygous ACTN2 p.Met228Thr variant was originally identified in a four-generation Italian family with atypical Hypertrophic Cardiomyopathy." (PMID 36899856, 2023). "Recent studies have demonstrated that ACTN2 deficiency affects the binding characteristics of actin as well as cardiomyocyte Z-discs and influences the formation of hypertrophic cardiomyopathy." (PMID 30651404, 2019). "Mutations in ACTN2 have been extensively associated with hypertrophic cardiomyopathy." (PMID 32824180, 2020). "We have discovered that two mutations at the actin binding domain (ABD) of α-actinin-2 (ACTN2), which cause hypertrophic cardiomyopathy (HCM), have minor effects on its structure and ability to bind actin and integrate into Z-discs, providing a potential disease mechanism." (PMID 27287556, 2016). "ACTN2 mutations are associated with a range of cardiac phenotypes, including but not limited to dilated cardiomyopathy (DCM) and hypertrophic cardiomyopathy (HCM)." (PMID 32824180, 2020).
distal myopathy (5 papers, 2021 to 2026). Distal myopathy refers to a group of muscle diseases which share the clinical pattern of predominant weakness and atrophy beginning in the feet and/or hands. "In conclusion, we identified a novel ACTN2 pathogenic variant as the cause of adult‐onset distal myopathy with multi‐minicores in a Chinese family." (PMID 34170073, 2021). "In this study, we firstly reported a novel heterozygous pathogenic variant within ACTN2 causing distal myopathy with multi‐minicores in a Chinese family." (PMID 34170073, 2021). "Herein, we firstly identified a novel ACTN2 variant causing an adult‐onset distal myopathy with a morphological feature of multiple well‐defined minicores, which, interestingly, was more like a combination of MsCD and actininopathy." (PMID 34170073, 2021). "In 2019, ACTN2 gene was firstly identified to be a cause of a new adult‐onset distal muscular dystrophy calling actininopathy and another distinctly different myopathy, named multiple structured core disease (MsCD)." (PMID 34170073, 2021). "Recently, however, ACTN2 mutations have been associated with novel congenital and distal myopathy." (PMID 36116040, 2022). "A rare adult‐onset distal myopathy with multi‐minicores caused by a novel ACTN2 mutation." (PMID 34170073, 2021). "In ACTN2-related distal myopathy, the first recessive forms of the disease have been described, adding it to the growing list of genes were both dominant and recessive forms of myopathy are present." (PMID 39017652, 2024). "Until recently, only autosomal dominant forms of ACTN2-related distal myopathies had been described." (PMID 39017652, 2024). "Generally, ACTN2-related distal myopathies begin with foot drop due to muscle weakness in the anterior compartment of the lower leg." (PMID 39017652, 2024). "Although myofibrillar features are the most common characteristics in various distal myopathies caused by genes encode Z‐disk or Z‐disk relevant protein, it seems that no aggregates are found in muscle biopsy of ACTN2‐related myopathy." (PMID 34170073, 2021).
cardiac hypertrophy (3 papers, 2015 to 2021). "Then, the changes in the expression of two cardiac hypertrophy‐specific genes, namely ACTN2 and ANP, in the primary myocardium with overexpressed or silenced MBNL1 were detected using realtime PCR and Western blotting." (PMID 33295096, 2021). "Similarly regulated transcripts between previous studies utilizing TAC-induced cardiac hypertrophy and this study include Acta1, MybpC2/3, Actn2, and Myh7 among others indicating an appropriate hypertrophic gene transcriptional response in WT mice." (PMID 26192751, 2015).
congenital myopathy (3 papers, 2021 to 2025). "Certain pathological variants of ACTN2 also influence the function and developmental process of skeletal muscles, causing congenital myopathy." (PMID 38316882, 2024).
restrictive cardiomyopathy (3 papers, 2024 to 2025). A type of heart disorder referring to the inability of the ventricles to fill with blood because the myocardium (heart muscle) stiffens and looses its flexibility. "We also identified a variant in a miRNA binding site of ACTN2 (chr1:236927207), a gene for which we and others recently demonstrated that protein-truncating variants cause hypertrophy and restrictive cardiomyopathy (RCM) in humans." (PMID 40791945, 2025).